INS (insulin)
Diseases named in the same sentence as INS in open-access papers (continued):
Sharing a sentence is not in itself a finding about the gene and the disease.
type 2 diabetes (continued). "Thus, improving tissue sensitivity to insulin and enhancing insulin secretion are two ways to treat type 2 diabetes." (PMID 38004234, 2023). "When beta cells create insulin, but the body is unable to use it, type 2 diabetes results." (PMID 36832207, 2023). "However, a link between primary cilia and obesity, insulin signalling, and type 2 diabetes have been described, which makes crosslinks to the lipoprotein metabolism not unlikely." (PMID 37834292, 2023). "Therefore, we performed a glucose clamp test and meal tolerance test (MTT) to evaluate whole-body insulin clearance and hepatic insulin clearance in overt type 2 diabetes." (PMID 38115089, 2023). "Longer duration of type 2 diabetes, existing DR or other microvascular complications, higher baseline HbA1c, as well as the insulin treatment may also be significant predictor of this effect." (PMID 38239984, 2023). "Selective intervention to restore GIV expression or function may delay the need for insulin therapy in type 2 diabetes." (PMID 36822326, 2023). "Excess SeP impairs insulin secretion from the pancreas and insulin sensitivity in skeletal muscle, thus inhibition of SeP could be a therapeutic strategy for type 2 diabetes." (PMID 37857700, 2023). "Our results might make the increased HIC in type 2 diabetes merely an assessment of decreased insulin secretion." (PMID 38115089, 2023). "Furthermore, the combination of thiazolidinediones and insulin in the therapies of type II diabetes is effective." (PMID 36846049, 2023). "TRPM5 plays a major role in glucose‐induced insulin secretion beyond membrane depolarization, and its dysfunction may lead to the occurrence and development of type 2 diabetes." (PMID 38107122, 2023). "Furthermore, it reduced fasting insulin levels and improved insulin sensitivity in obese mice and mice with type 2 diabetes." (PMID 38067472, 2023). "Salicylate treatment was able to overcome the inhibition of insulin signalling by TNF stimulation, implying that the IKKβ pathway may contribute to IR in Type 2 Diabetes and obesity by impinging on insulin signalling." (PMID 36175539, 2023). "The most significant effects of GLP‐1 involve regulating blood glucose levels in individuals with type 2 diabetes by promoting glucose‐dependent insulin release, inhibiting glucagon production, stimulating the growth of beta cells, enhancing insulin secretion, and curbing weight gain." (PMID 38093651, 2023). "Seventy‐two adults with type 2 diabetes and an HbA1c ≤ 7.5% (58 mmol/mol) treated with multiple daily insulin injections (MDI) participated in the trial (age 63.8 ± 9.5 years, HbA1c 6.4 ± 0.7%, [46 ± 8 mmol/mol] body weight 92.95 ± 18.83 kg, total daily insulin dose: 43.21 ± 10.80 units; mean ± SD)." (PMID 36461758, 2023). "Therefore, linoleic acid and alpha-linolenic acid generally play major roles in human health by reducing the risks for cardiovascular diseases and type 2 diabetes and improving long-term glycaemic control and insulin resistance." (PMID 37840730, 2023). "Importantly, decreased serum ghrelin levels and improved insulin sensitivity have been reported in patients with type 2 diabetes mellitus (T2DM) that underwent RYGB or sleeve gastrectomy." (PMID 37571301, 2023). "Just like in some patients with type 2 diabetes, the serum insulin level increases." (PMID 36742397, 2023). "In MR Egger, the p-values of MR Egger intercepts in each instrumental variable of Glycemic Traits were greater than 0.05, suggesting that the intercept does not exist, indicating fasting There was no horizontal pleiotropy for Fasting Glucose, 2-h Glucose, Fasting Insulin, HbA1c, and Type-2 Diabetes." (PMID 38179409, 2023). "However, to our knowledge, this is the first study to investigate the physiological response to hypoglycaemia induced by a basal insulin analogue in individuals with type 2 diabetes." (PMID 37308751, 2023).
type 2 diabetes (continued). "Independent genetic variants associated with insomnia, sleep duration, short sleep duration, body fat percentage, visceral adipose tissue (VAT) mass, type 2 diabetes, fasting glucose, and fasting insulin at the genome-wide significance level were selected as instrumental variables." (PMID 36895273, 2023). "Type 2 diabetes is characterised by progressive tissue insulin resistance." (PMID 37892985, 2023). "Many people require insulin therapy within 5–10 years of type 2 diabetes (T2D) diagnosis." (PMID 37237318, 2023). "The method was developed to measure the glucose/insulin ratio and could potentially be used to differentiate between type I and type II diabetes." (PMID 37504117, 2023). "Anti-diabetic activity: Flavonoids may help to regulate blood sugar levels and improve insulin sensitivity, which may be beneficial for people with type 2 diabetes." (PMID 37367648, 2023). "Furthermore, prolonged exercise training of at least moderate intensity improves TAC, insulin sensitivity, and HbA1c (%) levels, with improved adiposity markers in men with type 2 diabetes." (PMID 37512013, 2023). "By contrast, energy restriction induced by Roux-en-Y gastric bypass (RYGB) surgery of obese subjects with normal glucose tolerance, and obese patients with preoperatively type 2 diabetes, increased hepatic insulin clearance (=normalized) significantly within one week after operation." (PMID 36901984, 2023). "We found five genes that were candidates for selection in the four agricultural populations but not in the hunter-gatherer population (the Chabu); one has a possible relationship to subsistence strategy (PASK), which regulates insulin gene expression and can play a role in Type 2 diabetes." (PMID 37146165, 2023). "Evidence suggests that males might develop type 2 diabetes at lower BMI thresholds and might be more insulin resistant than females." (PMID 37356446, 2023). "Type 2 diabetes (T2D), also known as adult-onset diabetes, is a common metabolic disorder characterized by the inability of cells to respond properly to insulin hormone mediating cellular glucose uptake and/or insufficient insulin production by pancreatic beta cells." (PMID 38057293, 2023). "There could be several reasons why this might be the case: Regular exercise and physical activity can help manage blood sugar levels and improve insulin sensitivity in people with type-2 diabetes." (PMID 37854404, 2023). "Furthermore, higher POA levels in humans are correlated with better insulin sensitivity, an improved lipid profile, and a lower incidence of type-2 diabetes and cardiovascular pathologies, such as myocardial infarction." (PMID 38313838, 2023). "Nevertheless, it should be noted that, with the current obesity epidemic, children and young adults may experience a combination of type 1 diabetes with features of insulin resistence and type 2 diabetes (or other forms of insulin resistence) at the same time." (PMID 38032368, 2023). "Moreover, it has been shown that gastric bypass surgery in type 2 diabetes corrects and normalizes plasma insulin levels within some days after surgery, even though there is, at that moment, no significant weight loss (yet) and insulin resistance remains high." (PMID 36901984, 2023). "There is evidence from RCTs that rtCGM reduces HbA1c and increases TIR in people with type 2 diabetes treated with multiple daily injections or basal insulin, and is more effective than SMBG in minimizing hypoglycemia for people using therapies at high hypoglycemic risk." (PMID 37676398, 2023). "Insulin also significantly affects lipid metabolism, and people with less well-controlled type 1 diabetes or type 2 diabetes often have elevated levels of triglyceride-rich lipoproteins (VLDL and chylomicrons) and their partially metabolized remnants, which are believed to be highly atherogenic." (PMID 37378396, 2023).
type 2 diabetes (continued). "Insulin and glucagon can activate the transport of glycogen kinase by glucose transporters, modifying the amount of glycogen kinase in the cytoplasm of hepatocytes and managing the intracellular glucose content for the management of type 2 diabetes." (PMID 37894680, 2023). "Anti-diabetic activity: Catechins may help to regulate blood sugar levels and improve insulin sensitivity, which may be beneficial for people with type 2 diabetes." (PMID 37367648, 2023). "In type 2 diabetes, glucose, insulin, C-peptide, glucose-dependent insulinotropic peptide and glucagon-like peptide-1 increased further (P < 0.05), whereas triacylglycerol, ghrelin and plasminogen activator inhibitor-1 concentrations were significantly lower compared to the OW group (P < 0.001)." (PMID 37855336, 2023). "People who are overweight, insulin resistant, or have type 2 diabetes also showed this inhibition." (PMID 37346355, 2023). "Elucidating the molecular mechanism of HFD-induced translational repression of HK2 may lead to a novel strategy in the treatment of insulin insensitivity and type 2 diabetes." (PMID 36920797, 2023). "Furthermore, PPARγ activation in type 2 diabetic patients results in a marked improvement in insulin and glucose parameters by modifying whole-body insulin sensitivity." (PMID 37513660, 2023). "Insulin therapy: The administration of exogenous insulin is indispensable for the management of type 1 diabetes and often becomes necessary in the later stages of type 2 diabetes." (PMID 37965396, 2023). "On the other hand, insulin secretory capacity can be lost through β cell death and dedifferentiation; some data suggest the reduction of β cell mass in human type 2 diabetes (T2D) may have been overestimated." (PMID 37712417, 2023). "Furthermore, impaired insulin-stimulated glucose transport into muscle is an early event in the progression to type 2 diabetes in humans." (PMID 37248992, 2023). "This means that there is a potential selection bias in the study subjects that might limit the representativeness of our findings and their generalizability to other people with type 2 diabetes receiving insulin therapy." (PMID 37324170, 2023). "Type 2 diabetes is brought on by insulin resistance and a little insulin shortage." (PMID 37370932, 2023). "Vitamin D deficiency could potentially lead to insufficient insulin levels by disturbing insulin synthesis and secretion and accelerate the development of type 2 diabetes, obesity and metabolic syndrome." (PMID 37644450, 2023). "Women with a history of GDM show lower insulin sensitivity and the risk of developing type 2 diabetes is significantly increased compared to women without a history of GDM." (PMID 38292769, 2023). "Over the last decade, several cellular and animal studies have suggested that LXA4 may have a direct effect on the adipocyte insulin signaling pathway, thereby preventing the development of type 2 diabetes mellitus (T2DM)." (PMID 36742389, 2023). "Moreover, clinical studies imply that the temporary limitation of exaggerated insulin secretion (“β-cell rest”) in humans with type 2 diabetes delays β-cell dysfunction." (PMID 38203600, 2023). "Moreover, previous studies have shown that the incretin effect, which leads to an insulin secretion from the beta-cell following oral carbohydrate administration, is also impaired in people with obesity and ultimately in those with type 2 diabetes." (PMID 36771218, 2023). "Studies in patients with chronic insomnia and objective short sleep exhibit altered insulin-IGF-1 signaling, reporting lower levels of plasma insulin, which could increase the predisposition to develop type II diabetes." (PMID 36583849, 2023). "Moreover, genistein improved insulin sensitivity, serum triglyceride concentrations, and delayed the onset of type 2 diabetes." (PMID 37513660, 2023).
type 2 diabetes (continued). "Type 2 diabetes is characterized by reduced insulin sensitivity, elevated blood metabolites, and reduced mitochondrial metabolism with reduced expression of genes governing metabolism such as peroxisome proliferator-activated receptor gamma coactivator 1-alpha (PGC-1α)." (PMID 37325367, 2023). "Mean glycemic metrics for users with type 1 diabetes or non–insulin-treated type 2 diabetes." (PMID 36602920, 2023). "Whether glucagon-induced insulin secretion mediated via the GLP1R occurs to a greater extent in type 2 diabetes is unknown." (PMID 37751301, 2023). "Therefore, the contribution of KLB is associated with increased sensitivity to the beneficial effects of FGF21 on obesity and type 2 diabetes, including regulation of body weight, plasma lipid levels and insulin sensitivity." (PMID 37019912, 2023). "For example, some of the anti-diabetic drugs such as biguanides, SGLT2 inhibitors, DPP-4 inhibitors, sulfonylureas, and insulin, which have been commonly administered for the management of type-2 diabetes, are reported to exacerbate the clinical conditions in COVID-19." (PMID 36839456, 2023). "In diabetology, verapamil may improve insulin sensitivity and glucose metabolism, benefiting type 2 diabetic patients." (PMID 38089049, 2023). "For instance, women with type 2 diabetes could have been recently diagnosed, may switch to insulin injections during pregnancy from usual oral medications, and are less likely to have had specialized preconception care and counselling." (PMID 37131168, 2023). "Human Actrapid insulin successfully treated one patient who had type II diabetes." (PMID 37398765, 2023). "The results of this indirect treatment comparison demonstrate that, among patients with type 2 diabetes uncontrolled on basal insulin, treatment with IDegLira resulted in a greater reduction of HbA1c and higher odds of reaching HbA1c < 7% compared with iGlarLixi." (PMID 36726134, 2023). "Taking that into account, authors applied additional inclusion criteria to differentiate type 1 and type 2 diabetes by using a minimum onset age of 45 years, conjointly applied with insulin delivery or LTD, before which patients were assumed to have type 1 diabetes." (PMID 37322499, 2023). "We are currently inconclusive on the association of drinking, coffee intake, composition of diet structure, sedentary, insomnia, sleep duration, serum lipid, C-reactive protein, fasting insulin, type 2 diabetes, thyroid dysfunction, testosterone and oestradiol with OSA." (PMID 38085646, 2023). "Scientific literature reports that rising NAD+ levels influence several different conditions and illnesses, such as metabolic syndrome, type 2 diabetes and/or insulin sensitivity, cancer, cardiovascular disease, neurodegeneration, renal function and Alzheimer’s disease." (PMID 36769283, 2023). "It has long been thought to be an aspect of the progress of type II diabetes, even though the molecular mechanisms relating to insulin resistance and fatty acids are still unknown." (PMID 37241737, 2023). "Obesity is a prevalent global health issue that increases the risk of developing type 2 diabetes mellitus (T2DM), a condition characterized by hyperglycemia resulting from insulin resistance and pancreatic β-cell failure, leading to insufficient insulin secretion." (PMID 37298086, 2023). "Therefore, the current study aimed to further scrutinise the effect of vitamin K supplementation in the form of vitamin K4 on insulin resistance, glycaemic control, and lipid profile of individuals with type 2 diabetes." (PMID 37552330, 2023). "Moreover, rIL-22 also controls type 2 diabetes (T2D) by lowering insulin and improving serum lipid metabolism." (PMID 36839448, 2023). "Insulin therapies were more frequent in type 1 diabetes compared to type 2, while oral antidiabetics, antihypertensive, and statin therapy were more prevalent in the type 2 diabetes cohort." (PMID 37189645, 2023).
type 2 diabetes (continued). "Significantly, those with higher post-meal ratios faced a greater risk of uncontrolled blood sugar, suggesting that an imbalanced high glucagon to insulin ratio could impair glucose control in type 2 diabetes patients." (PMID 37762748, 2023). "All clinical and anthropometric measurements relevant to type 2 diabetes including HbA1c, C-peptide, insulin, low-density lipoprotein, high-density lipoprotein, total cholesterol, triglycerides, and BMI, are summarized for mean values by gender to identify any outliers in the data." (PMID 36869348, 2023). "Previous studies have failed to illustrate an essential aspect, i.e., if SGLT2i pharmacotherapies for type 2 diabetes have a permissive or additive effect on the dose of insulin and if they exert any impact on the methods used to achieve carbohydrate restrictions." (PMID 36804863, 2023). "It was reported that the decreased hexokinase II expression during physical inactivity could trigger an alteration similar to type 2 diabetes, such as altered insulin response and muscle glucose transport." (PMID 37686852, 2023). "Therefore, when glucose of patients with type 2 diabetes is high, we can choose dulaglutide combined with insulin degludec to achieve a more stable hypoglycemic effect." (PMID 37255975, 2023). "Thus, it is not surprising that little was known about the prevalence of hyperinsulinemia and its potential clinical value in patients with type 2 diabetes who were treated with insulin or insulin analogs." (PMID 37324170, 2023). "Therapies aimed at preventing or reversing the regression of pancreatic insulin-producing cells could restore healthy sugar metabolism in individuals with type 2 diabetes." (PMID 37524865, 2023). "Improvement of insulin secretion by pancreatic β-cells and preservation of their mass are the current challenges that future antidiabetic drugs should meet for achieving efficient and long-term glycemic control in patients with type 2 diabetes (T2D)." (PMID 36980281, 2023). "Treatment for type II diabetes mellitus may become an earlier start of the insulin therapy to preserve the remaining pancreatic insulin reserve." (PMID 36846049, 2023). "Besides, FGF21 increased insulin content in primary islets in a rat model of type 2 diabetes and increased beta cell number in a mouse model of type 2 diabetes." (PMID 36331598, 2023). "High levels linoleic acid can reduce the risk of type 2 diabetes, fasting blood glucose, and glycated hemoglobin, but has no significant relation with fasting insulin." (PMID 38075067, 2023). "Type 2 diabetes occurs when body cells or organs are insensitive to the presence of insulin in circulation, and pancreatic β-cells fail to produce enough insulin to compensate for the ongoing insulin resistance." (PMID 36837910, 2023). "The same degree of weight loss can improve insulin sensitivity and reduce medication requirements in patients with type 2 diabetes, although it does not guarantee complete resolution." (PMID 38130527, 2023). "The successful transfer of the individual carrying this variant from insulin pump therapy to an oral short-acting meglitinide proves that she did not have type 1 diabetes but does not exclude the possibility of type 2 diabetes." (PMID 36418577, 2023). "Thus, the data suggest that the HbA1c gap between two consecutive visits appears to play a crucial role in the decision to start insulin therapy in a person with type 2 diabetes." (PMID 36889912, 2023). "Type 2 diabetes (T2D) is a metabolic disorder that is categorized by hyperglycemia resulting from failings in insulin secretion from β cells of the pancreas and insufficient insulin action." (PMID 37215217, 2023). "Diabetes type 2 may be associated with INSR, which involved in adipogenesis and beta-cell insulin secretion." (PMID 37063851, 2023). "The failure of metabolic tissues to respond to insulin is an early marker of type 2 diabetes." (PMID 36808134, 2023).